LINC02574 (long independently transcribed non-coding RNA 2574)
Synonyms: RP11-288L9.1; HEAL
Gene: Long non-coding RNA gene on chromosome 1 (27,660,327 to 27,666,279, reverse strand). Ensembl gene ENSG00000233975.
Diseases named in the same sentence as LINC02574 in open-access papers:
LINC02574 is named in the same sentence as 10 diseases in open-access papers, as found by Europe PMC text mining. Sharing a sentence is not in itself a finding about the gene and the disease. The quoted sentences say what the papers report.
viral infection (2 papers, 2020 to 2023). "Therefore, LINC02574 may play different roles by targeting different pathways in different viral infections." (PMID 37108410, 2023). "In this study, knockdown of LINC02574 in A549 cells attenuated the expression of multiple ISGs and type I and type III IFNs, as well as the activation of STAT1 triggered by IAV infection, indicating that LINC02574 positively regulates the innate immune response to viral infection." (PMID 37108410, 2023).
infection (2 papers, 2023). The state of being infected such as from the introduction of a foreign agent such as serum, vaccine, antigenic substance or organism. "A549 cells were infected with WSN of different multiplicities of infection (MOI), and WSN significantly upregulated LINC02574 in a concentration-dependent manner." (PMID 37108410, 2023).
LINC02574 also shares sentences with these, for which no sentence is quoted: AIDS (4 papers); HIV-1 infection (2); COVID-19 (1); leishmaniasis (1); leprosy (1); malaria (1); sarcoma (1); tuberculosis (1).